EPCAM (epithelial cell adhesion molecule)
Diseases named in the same sentence as EPCAM in open-access papers (continued):
Sharing a sentence is not in itself a finding about the gene and the disease.
tumor (continued). "Nonspecific capture, when it occurs, can be attributed to other non-tumor cells, such as CD11b+ cells, as noted in previous studies on EpCAM-based CTC detection." (PMID 39337304, 2024). "Tumor cells (AS‐OV), either as single cells or tumorspheres, were isolated from fresh ascites using EpCAM+ selection and cultured in 2D or 3D conditions for subsequent experiments." (PMID 38010623, 2024). "The association of EpCAM with pathways like PI3K/AKT signaling and its regulation by factors such as EGF via ERK1/2 signaling elucidates its part in tumor progression and resistance mechanisms." (PMID 39033780, 2024). "This is corroborated by the evidence that cisplatin resistance in tumor cells is induced by an EpCAM–claudin–tetraspanin complex and an Nrf2–EpCAM axis." (PMID 38791091, 2024). "We employed inferCNV to predict copy number variations to identify distinct copy number profiles in EPCAM-positive tumor cells compared to non-tumor cells." (PMID 39122703, 2024). "These aptamers have high binding affinity to and demonstrate specificity for EpCAM expressed on CCA tumor cells." (PMID 39513807, 2024). "Overall, 99 (82.5%) of 120 tumor categories showed detectable EpCAM expression and 85 (70.8%) tumor categories contained at least one case with strong positivity." (PMID 38786342, 2024). "While dual functionalities of EpCAM in the context of cancer are thought to exist, the mechanistic insights behind its pro-tumor characteristics have been well established." (PMID 39010070, 2024). "We then sorted GFP+ tumor cells, including both EpCam+ and EpCam- cells, from the lungs for scRNA-seq analyses." (PMID 39259576, 2024). "Herein we show spatial associations between regional clustering of tumor NOS2 and specific EpCAM+ cellular neighborhoods along the tumor margin and in the stroma in tumors from deceased patients at 5-year survival." (PMID 39356141, 2024). "Since EpCAM regulates cell adhesion, proliferation, migration, and EMT, overexpression of EpCAM is directly linked to tumor formation and poor differentiation grade." (PMID 39349424, 2024). "Induction of Siglec signalling by either EpCAM+ tumor cells or stromal regions remains an interesting subject for future studies." (PMID 39246414, 2024). "The GILUPI CellCollector, an approved medical device, operates on the principle of utilizing antibodies against epithelial adhesion molecules (EpCAM) to capture tumor cells." (PMID 39503055, 2024). "Hep3B cells treated with EpCAM-apt-Dox formed smaller and fewer tumor spheres than the control group." (PMID 39192365, 2024). "Although the potential use of EpCAM as a multi-tumor target is promising, including epithelial-derived GC, challenges remain in optimizing the specificity and safety of these agents for clinical applications." (PMID 39766041, 2024). "The administration of intratumoral injection of VV-EpCAM BiTE demonstrated a significant enhancement in the efficacy of tumor suppression within EpCAM-positive tumor models, when compared to the administration of wild type of vaccinia virus." (PMID 38464532, 2024). "Anti-EpCAM CAR-T cells have also been shown to produce robust anti-tumor responses in gastric cancer SNU-638 and MKN-45 and pancreatic Capan2-Fluc+ models in mice, with complete responses maintained in nearly all the mice." (PMID 38612911, 2024). "In contrast, many studies have reported pro-tumor functionalities of EpCAM in patient samples for some of the same cancer types." (PMID 39010070, 2024). "To substantiate this classification, we examined the expression of hallmark canonical cell markers of cancer epithelial cells (EPCAM, SOX4, KRT7, KRT18, KRT19, KRT8) in C1 (normal epithelial cells) and the other clusters (tumour epithelial cells)." (PMID 38445456, 2024). "EpCAM has been popularly used for targeting tumor cells circulating in the bloodstream; however, it has been shown that there are CTCs devoid of EpCAM expression, as well as non-CTCs expressing EpCAM in the blood of cancer patients." (PMID 39459070, 2024).
tumor (continued). "It is a hybrid rat–mouse mAb with an epithelial cellular adhesion molecule (EpCAM) binding arm (mouse IgG2a) and a CD3 binding arm (rat IgG2b), enabling it to simultaneously bind to EpCAM on tumor cells and CD3 on T cells." (PMID 39339191, 2024). "Currently, EpCAM is still considered a specific prognostic cancer marker because it is involved in the processes of tumor progression and metastasis." (PMID 39199590, 2024). "Subsequently, we digested the tumor tissues into single cells and sorted the tumor cells using EpCAM antibodies to assess the levels of ROS accumulation and apoptosis rate in each group of cells." (PMID 39286657, 2024). "Elevated EpCAM expression is observed in a diverse spectrum of neoplasms, UC included, and is correlated with advanced stage, elevated histological grade, and diminished OS in patients with BC." (PMID 38665947, 2024). "We conducted an immunohistochemistry analysis to evaluate the proportion of tumor cells expressing EpCAM on tissue slides obtained from 11 BC patients." (PMID 39456890, 2024). "In conclusion, we demonstrated that locally injected CAR T-cell adjacent to the tumor lead to intratumoral accumulation and reduced tumor growth translating into a survival benefit of EpCAM/GFPCAR T-cell-treated mice." (PMID 39358663, 2024). "Another study revealed that colorectal CSCs can fuse with monocytes to form CD45+CD14+EpCAM+ tumor hybrid cells (THCs), which exhibit higher metastatic and immune escape capacities." (PMID 38254219, 2024). "Since only 3–5% of live cells in these isolates were tumor cells as judged by EpCAM staining, these analyses detect relative changes in immune cell populations in the tumor." (PMID 38365788, 2024). "Its expression on treatment-resistant cancer stem cells, along with its abundance in the CCA tumor microenvironment, highlights the need to develop EpCAM-targeted therapies for CCA." (PMID 39513807, 2024). "After inoculation of 2.5 × 103 EpCAM/tdtLL/2 tumor cells, all mice (n = 8 per group) had visible tumors at day 5 after tumor cell injection." (PMID 39358663, 2024). "Tumor CD44v6 and EpCAM expressions have been used as clinical CSC markers in breast and other cancers, correlating with metastasis, circulating tumor cells, CSC, and chemoresistance." (PMID 39356141, 2024). "The GILUPI CellCollector, an established medical device, utilizes antibodies against epithelial adhesion molecules (EpCAM) to capture circulating tumor cells (CTCs) from peripheral blood." (PMID 39503055, 2024). "To focus on TNBC cell populations within the VMT, we integrated the MDA-MB-231 VMT and HCC1599 VMT datasets and subset the tumor cells from the EPCAM+ or KRT18+ clusters in the individual datasets for further investigation." (PMID 38183074, 2024). "A similar phenomenon is observed in epithelial cell adhesion molecule (EpCam)-positive BC cells treated with the EpCam-specific antibody C215, suggesting a potential connection between EV release and tumor progression." (PMID 39513123, 2024). "Although tumor-promoting functionalities of EpCAM have been extensively reported, several studies have also revealed that EpCAM exerts tumor-suppressing properties in many cancer types." (PMID 39010070, 2024). "Epithelial-cell adhesion molecule (Ep-CAM) and 14-3-3 protein theta showed the lowest levels in both the tumor regions here analyzed." (PMID 39195201, 2024). "Siglec‐7 ligands were predominantly found on the EpCAM+ tumor cells and to a lesser extent on tumor stroma, whereas Siglec‐9 ligands were expressed on both the EpCAM+ tumor cells and also highly on the tumor stroma." (PMID 39246414, 2024). "They designed ROR1-directed CAR-T cells to co-express EpCAM or B7-H3-specific synthetic notch receptors which functioned as a logic gate to restrict CAR-T cell activity to tumor cells that expressed the ligands for the synthetic notch receptors." (PMID 39796666, 2024).
tumor (continued). "The combined use of rVAR2 and anti-EpCAM antibodies significantly enhanced tumor cell recovery compared with using either alone." (PMID 39337304, 2024). "Engineered to latch onto liver cancer cell-specific markers, such as GPC3 and EpCAM, AFNs usher in tumor-focused therapy, sparing healthy cells and elevating treatment safety and efficacy." (PMID 38735927, 2024). "Immunohistochemical staining of tumors for EpCam (epithelial marker) and vimentin (mesenchymal marker) showed that the fraction of epithelial, EpCam-positive, cells was more than 90% in tumor xenografts and on average 76 ± 10% in patients’ tumors." (PMID 39197048, 2024). "The role of EpCAM in conferring migratory and invasive capabilities to tumor cells is, in part, attributed to its involvement in epithelial–mesenchymal transition (EMT) development." (PMID 39456890, 2024). "Given its strong expression on epithelial cells and epithelial cell-derived tumors, EpCAM has been identified as a biomarker for circulating tumor cells (CTCs) and exosomes and a target for cancer therapy." (PMID 38791091, 2024). "CK8 (KRT8), CK18 (KRT18), and EPCAM were expressed differentially (upregulated) in TRG5 tumours, but undetectable in the regressed lesion." (PMID 38630793, 2024). "We confirmed that the pkg1 staining was specific to pericytes by co-staining with CD26,CD45, and EpCAM, which allowed us to exclude fibroblasts, leukocytes, and epithelial tumor cells, respectively." (PMID 39741968, 2024). "Hereto, the tumor cells were single cell-sorted by their expression of epithelial cell adhesion molecule (EpCAM)." (PMID 39009951, 2024). "In conclusion, our research revealed that a novel germline-like fully human antibody with nanomolar binding affinity against EpCAM, fused with a biased IL-2v, exhibits potent anti-tumor activities." (PMID 39595576, 2024). "During epithelial-mesenchymal transition (EMT), a process central to cancer metastasis, tumor cells frequently downregulate or lose EpCAM expression, further reducing the method’s effectiveness in identifying specific CTC subsets." (PMID 39886667, 2024). "After 3 days of co-culture in medium with low serum and physiologic concentrations of glucose, we recovered cancer cells using EpCAM immunomagnetic beads, capitalizing on expression of EpCAM exclusively on tumor cells of epithelial origin." (PMID 39480488, 2024). "Of note, EpCAM has been reported to act via EpEX and EpICD to influence critical cell signaling pathways that promote tumor progression." (PMID 39010070, 2024). "This approach has been employed in studies targeting tumor cells via tumor-associated antigens such as HER2, EGFR, and EpCAM or immune cells through immunological receptors like CD20, CD19, CD8, CD4, and CD30." (PMID 39772246, 2024). "In the course of our investigation, we conducted a comprehensive analysis encompassing thirty-three different tumor types to scrutinize the expression patterns of EpCAM." (PMID 38187284, 2024). "Epithelial cell adhesion molecule (EpCAM) has been widely studied as a tumor antigen due to its expression in varieties of solid tumors." (PMID 39010070, 2024). "The results showed that compared with control group and DS-8201 treatment group, phosphorylation of TBK1 in EpCAM+ xenograft tumor cells was much higher in the ADU-S100 treatment group and combined treatment group." (PMID 38993569, 2024). "The secretion of serum killer cytokines TNF-α and IFN-γ in tumour-bearing nude mice in the experimental group treated with EpCAM-CAR-T cells was higher than that in the blank and control groups (P < 0.05)." (PMID 39107717, 2024).
tumor (continued). "We also show that EpCAM+Vim+CD24- tumour cells in the stroma do not correlate with metastasis, and therefore the clinically predictive utility of tumour cell staining in the stroma can be isolated specifically to the EpCAM+Vim+CD24+ EMT CSCs." (PMID 37975646, 2023). "This indicates that EpCAM, a marker of epithelial cells, cannot bind to mesenchymal-type tumor cells." (PMID 37569448, 2023). "It was designed in EpCAM-specific CARs and introduced into human peripheral blood lymphocytes (PBLs); results suggested that EpCAM-specific PBLs significantly inhibit PC-3 tumor cell growth in vitro and in vivo by targeting PCSCs." (PMID 36969009, 2023). "We therefore systematically investigated and quantified the tumor specificity of EpCAM in UC—including its understudied proteoforms as possible confounders." (PMID 37154925, 2023). "We used syngeneic murine tumor models expressing the human EpCAM target (C215 antigen) to assess the efficacy and mechanism of action of repeated treatment with TTS C215Fab-SEA alone or with anti-PD-1/PD-L1 monoclonal antibodies." (PMID 36967382, 2023). "We also found that softening cells enhanced the formation and growth of tumor spheroids and the percentage of EpCAM+ and CD90+ cells in several other HCC cells (Hep3B, HepG2, MHCC97L)." (PMID 37746658, 2023). "Utilizing this knowledge, a novel tumor-targeted AAV vector called EpCAM-AAV was developed by incorporating these EpCAM-specific DARPins directly into the AAV2 capsid." (PMID 38082377, 2023). "Granzyme B fusion proteins targeting EpCAM significantly inhibited tumor growth by ≤ 50% in mice inoculated with human TNBC cells." (PMID 37457288, 2023). "We next stratified 24 human primary OSCC specimens into 12 tumours that had evidence of lymph node metastasis or perineural spread, and 12 that remained metastasis free, and stained them for EpCAM, Vimentin and CD24." (PMID 37975646, 2023). "The shift toward a more epithelial phenotype was confirmed by increased EpCAM IHC staining in tumour samples from patients treated with NP137." (PMID 37532934, 2023). "We next evaluated the anti-tumor effect of VH-F12 because cell surface EpCAM plays a major role in the recognition of receptors and ligands." (PMID 37834237, 2023). "For CTC capture, in most cases, the antigen of relevance is the epithelial cell adhesion molecule (EpCAM), an antigen that is overexpressed in most cancers of epithelial origin in both tumour tissue and CTCs6." (PMID 37055551, 2023). "Smarcd3KO-KPf/fC tumors showed a trend towards reduced EpCAM+ tumor cell content, and a 2.5-fold reduction in EpCAM+MSI2+ cancer stem cells at midpoint (7–8 weeks)." (PMID 36653361, 2023). "Similar to normal mammary glands, CD45-/CD90.2 + fibroblasts specifically expressed Has1 whereas EpCAM + epithelial cells expressed elevated levels of Has3 in the HC11/R1-LM tumor model." (PMID 36723776, 2023). "In the triple-negative tumors, FN-EDA staining was the most prominent in the EpCAM-expressing tumor cells." (PMID 36922898, 2023). "Using transfection of nuclear actin chromobody in different tumor cells, researchers found an increase in nuclear actin filament in EPCAM− cells compared to that in EPCAM+ and RHOJ-KO EPCAM−cells, suggesting that RHOJ modulates nuclear actin polymerization." (PMID 37779170, 2023). "EpCAM cleavage through regulated intramembrane proteolysis results in fragments which interact with both oncogenic and tumor suppressive pathways." (PMID 37154925, 2023). "Prognostic significance of urinary EpCAM is most likely due to correlation with the amount of shredded tumor cells in higher grade tumors." (PMID 37154925, 2023). "To test this possibility, we investigated the presence of actin fibres in the nucleus using transfection of nuclear actin chromobody in EPCAM+, EPCAM− and Rhoj-KO tumour cells isolated from Lgr5creERKrasG12DTrp53cKORosa-tdTomato mice." (PMID 36949199, 2023).
tumor (continued). "Immunofluorescence examination also showed that colocalization of VAChT with EpCAM, a marker of epithelial cells, was profoundly increased in lungs from tumor-bearing mice in both the stress and the Un-pre groups." (PMID 37773152, 2023). "HIF-1α can enhance the expression of many cancer stem cell phenotype markers as well as the epithelial cell adhesion molecule EpCAM, which can have increased expression during tumour cell growth and metastasis." (PMID 36879003, 2023). "Existing data on the prognostic role of EpCAM is equivocal, some suggesting a dual role as a tumour suppressor and an oncogene." (PMID 37533952, 2023). "CD45 fluorescent image analysis was performed on three representative tumor models with high EpCAM expression—CXF1103, CXF269 and GXA3067—with Z-plane high-content confocal analysis of infiltrating cells." (PMID 37190054, 2023). "In our study, we have taken a modular approach that combines the delivery of the Ras-cleaving enzyme RRSP with the ability to redirect its activity toward tumor cells that overexpress a specific marker, EpCAM." (PMID 37485031, 2023). "To further understand the cellular origin of this increased EMT marker expression, we conducted IHC for EPCAM to stain tumor epithelium as well as VIM and ZEB1 in murine and human samples." (PMID 38153787, 2023). "Both AFP and EpCAM-positive circulating tumor cells have previously been described to be highly specific tumor markers." (PMID 38012205, 2023). "Other studies reported that HE4, TFPI2, and epithelial cell adhesion molecule (EpCAM, CD326) are tumor markers, and recent studies have shown that miRNAs in peripheral blood are highly sensitive markers." (PMID 37712874, 2023). "In vivo, effectiveness was validated through an EpCAM-positive human tumor xenograft model in severe combined immunodeficiency (SCID) mice, with the majority of treated mice remaining tumor-free." (PMID 38133203, 2023). "The proportion of EPCAM+ to EPCAM− tumour cells was unchanged after Rhoj deletion, showing that RHOJ does not control EMT per se." (PMID 36949199, 2023). "Of note, ROR1- and EpCAM-positive lEVs were barely detectable in healthy controls, suggesting their tumor specificity." (PMID 37430307, 2023). "EpCAM is a widely used marker for epithelial cells and tumor cells, and MUC4 is commonly known to be expressed in early PanIN cells." (PMID 37964407, 2023). "After 8 days of culture, the structure of the OV tissue was preserved and the EpCAM+ tumor cells showed proliferation with Ki67 expression." (PMID 36899943, 2023). "In accordance with our results from the scRNA-Seq analysis, we found a strong dominance of the stromal compartment, visualized by a reduction of EPCAM+ tumor cells in PC." (PMID 38153787, 2023). "The most commonly used biomarker for identification and isolation of circulating tumor cells (CTCs) has been epithelial cell adhesion molecule (EPCAM)." (PMID 37720505, 2023). "In this study, we investigated 377 clones of fully human mAbs against a tumor antigen, epithelial cell adhesion molecule (EpCAM), to determine their antigen binding properties." (PMID 36918661, 2023). "The cell surface glycoprotein EpCAM is highly expressed on a variety of epithelial cancers but also in healthy tissues, successful therapeutic targeting relies on balancing on- and off-tumor effects." (PMID 36845124, 2023). "EpCAM is overexpressed in most epithelial tumors and is frequently used as a marker to identify circulating tumor cells and cancer stem cells." (PMID 37192201, 2023). "Detection of micro-metastases or surrogates of systemic tumor manifestation, e.g. circulating EpCAM-positive tumor cells (CTC), is considered to indicate more advanced disease states with worse prognosis." (PMID 38012205, 2023).